OTOP3 (otopetrin 3)
Description:
Proton-selective channel gated by extracellular protons.
Tractability: Antibody: UniProt places it where antibodies can reach, with medium confidence; UniProt predicts a signal peptide or a membrane-spanning region; its Gene Ontology location is reachable by antibodies, with medium confidence.
Gene: Protein-coding gene on chromosome 17 (74,935,883 to 74,949,992, forward strand). Ensembl gene ENSG00000182938.
Subcellular location: Cell membrane
Gene Ontology:
Molecular function: protein binding; identical protein binding; proton channel activity
Biological process: proton transmembrane transport
Cellular component: plasma membrane; membrane
Genetic constraint (gnomAD): Loss-of-function variants: 41 observed, 50.66 expected, observed/expected ratio (o/e) 0.81, 90% interval 0.63 to 1.05. The upper end of that interval is the gene's LOEUF score, 1.05, which puts it in group 4 of 6, group 1 being the genes least tolerant of losing a copy. Missense variants: 788 observed, 777.18 expected, observed/expected ratio (o/e) 1.01, 90% interval 0.95 to 1.08. Synonymous variants: 320 observed, 335.37 expected, observed/expected ratio (o/e) 0.95, 90% interval 0.87 to 1.05.
Homologues: Orthologues: chimpanzee OTOP3 (96% identical), macaque OTOP3 (93% identical), dog OTOP3 (86% identical), pig OTOP3 (85% identical), rat Otop3 (83% identical), mouse Otop3 (82% identical), guinea pig OTOP3 (81% identical), tropical clawed frog otop3 (39% identical), Caenorhabditis elegans otpl-3 (18% identical), Caenorhabditis elegans otpl-7 (18% identical), Caenorhabditis elegans otpl-8 (17% identical), Caenorhabditis elegans otpl-2 (17% identical), and 2 more. Paralogues in human: OTOP2 (39% identical), OTOP1 (31% identical).
Diseases named in the same sentence as OTOP3 in open-access papers:
OTOP3 is named in the same sentence as 7 diseases in open-access papers, as found by Europe PMC text mining. Sharing a sentence is not in itself a finding about the gene and the disease. The quoted sentences say what the papers report.
colon cancer (3 papers, 2020 to 2022). "OTOP3 has been reported as an interesting candidate for future research in colon cancer." (PMID 36293321, 2022).
colorectal cancer (3 papers, 2019 to 2024). A primary or metastatic malignant neoplasm that affects the colon or rectum. "A model for the early-stage screening of colorectal cancer was created using seven consensus biomarkers (namely ESM1, DHRS7C, OTOP3, AADACL2, LPHN3, GABRD, and LPAR1), and yielded >98% balanced accuracy on external validation." (PMID 39484215, 2024). "We also identified multiple down-regulated genes in colorectal cancer that are supported by recent studies on the gene products of the OTOP2, OTOP3, SPIB, and INSL5 genes." (PMID 37790614, 2023).
deafness (1 paper, 2011). An inherited or acquired condition characterized by the complete loss of the ability to hear from one or both ears. "We also extended our evolutionary studies to the Ush1g deafness gene because of the tight head-to-tail physical clustering of Ush1g with Otop2 and Otop3 in vertebrate genomes, and because mutations in Otop1 and Ush1g result in inner ear phenotypes in vertebrates." (PMID 21261979, 2011).
neuroblastoma (1 paper, 2018). Neuroblastoma (NB) is the most common solid, extracranial childhood tumor. "In fact, MYCN is one of the best characterized genetic alterations in neuroblastoma; and copy number gain of chromosome 17q, where OTOP3 is located, is a known neuroblastoma risk factor." (PMID 30012197, 2018).
Obesity (1 paper, 2017). Accumulation of substantial excess body fat. "Contrary to the other validated molecules, otopetrin 3 showed decreased levels in an obesity-related behaviour in both, 2D-DIGE and western blot." (PMID 28425473, 2017).
cancer (2 papers, 2019 to 2024). A tumor composed of atypical neoplastic, often pleomorphic cells that invade other tissues. "A summary of the models used for building a classifier capable of discriminating between cancer and normal samples based on the expression of seven features: ESM1, DHRS7C, OTOP3, AADACL2, LPHN3, GABRD, and LPAR1." (PMID 39484215, 2024). "A feature space of just seven biomarkers, namely ESM1, DHRS7C, OTOP3, AADACL2, LPHN3, GABRD, and LPAR1, was sufficient to optimize a RandomForest model that achieved > 98% balanced accuracy (and performant recall) of cancer vs. normal on external validation." (PMID 39484215, 2024). "For the other four genes (SGCG, CCDC78, OTOP3, and SMPDL3A) in the predicted scoring model, their roles in human cancers have not yet been fully investigated." (PMID 31612869, 2019).
OTOP3 also shares sentences with these, for which no sentence is quoted: diabetes (1 paper).